SOCS1 (suppressor of cytokine signaling 1)
Diseases named in the same sentence as SOCS1 in open-access papers (continued):
Sharing a sentence is not in itself a finding about the gene and the disease.
cancer (continued). "Methylation of SOCS1, another member of the SOCS family, has been shown to be hypermethylated and contribute to STAT3 activation in MM, a cancer that shares several similarities with PEL." (PMID 38534772, 2024). "The results indicated that the promoter methylation levels of SOCS1 (p– = 7.379E‐07), SOCS3 (p = 4.534E‐10), SOCS5 (p = 1E‐12), SOCS6 (p = 5.534E‐11), and CISH (2.273E‐05) were lower in cancer tissues than in normal tissues." (PMID 39307915, 2024). "SOCS1/3 are negative regulators of the IL-6/STAT3/NFKB axis, whose dysfunction leads to various cancers." (PMID 38023123, 2023). "The methylation status of SOCS1 and SOCS3 are evaluated in different cancers e.g., ovarian and breast carcinomas, Barrett’s adenocarcinoma, gastrointestinal cancers like hepatocellular carcinoma, pancreatic carcinoma, human lung, and head and neck cancer." (PMID 36609306, 2023). "A recent study also highlighted the role of H. pylori in the epigenetic silencing of SOCS1 in GC through hypermethylation of the promotor region, which in addition to inflammatory cytokines, further amplifies JAK-STAT signaling in this cancer." (PMID 35844493, 2022). "In particular, SOCS1 and SOCS3, as potent inhibitors of JAKs, were reported to be played a critical role in various malignant processes, such as in cancers." (PMID 35184640, 2022). "Tgfbr2 KO on cancer cells promotes TME remodeling and immune exclusion; Socs1 KO made the tumors more responsive to PD-L1 blockade." (PMID 36313703, 2022). "On the other hand, inhibition of negative regulators such as PIAS3, SOCS1 and 3 and several cellular phosphatases (SHP1 and 2, PTPRD, PTPRT, PTPN1 and 2, DUSP22) can also lead to STAT3 activation in cancer." (PMID 35145111, 2022). "SOCS1 and SOCS3 suppress cell growth and proliferation, and their expression is commonly downregulated in different types of cancer, including hematological malignancies such as ALL, CLL, and AML." (PMID 34439155, 2021). "Regarded as an “OncomiR,” miR-155-5p shows features of oncogenicity by targeting SOCS1, FOXO3 in multiple types of cancer cells." (PMID 34131104, 2021). "SOCS1 suppresses JAK-STAT signaling and cancer immunotherapy, and its mRNA levels were reciprocally controlled by ANKRD52 and CK1α." (PMID 34853298, 2021). "Correlation analysis between miR-155 gene expression and SOCS1, TAB2, and Foxp3 in cachectic pancreatic or NSCL cancer patients (Spearman’s correlation)." (PMID 34900737, 2021). "Among the identified DEGs, 5 candidate cancer-induced genes including BHLHE40, AREG, SOCS1, CCL5 and DDIT4 were selected for external validation on an independent set of PBMC samples of patients with various stages of HCC." (PMID 34045534, 2021). "SOCS1 and SOCS3 have been the most extensively studied amongst the SOCS family members in relation to cancer and inflammation." (PMID 34439155, 2021). "An example of gene-specific methylation change includes the cancer cell-induced methylation and concomitant downregulation of the SOCS1 gene in PDAC CAFs, which enhanced cancer cell growth through the STAT3/IGF1 axis." (PMID 32760726, 2020). "Recent studies have found that SOCS1 and SOCS3 genes are hypermethylated in various types of cancers." (PMID 32931454, 2020). "We further examined the expression of SOCS1 and STAT1 proteins in NPC tumors and para-carcinoma tissues by IHC." (PMID 32831137, 2020). "Although SOCS1 levels were comparative between the normal and cancerous tissues, it was NPC tumors instead of para-carcinoma tissues that exhibited a strong immunostaining signal of STAT1, indicating the interrupted Inhibition of SOCS1 on STAT1 in NPC tumors." (PMID 32831137, 2020). "The mechanisms that disable SOCS1 and SOCS3 in human cancers are often epigenetic, mediated either by miRNAs, promoter methylation or protein phosphorylation." (PMID 31557897, 2019).
cancer (continued). "The meta-analysis of GSTP1, RUNX3, SOCS1, CDH1 and SFRP1 genes methylation was performed between HBV-positive carcinoma tissues and HBV-negative carcinoma tissues and between HBV-positive adjacent tissues and HBV-negative adjacent tissues." (PMID 31772678, 2019). "Our meta-analysis was unable to find any statistical significance between HBV-positive carcinoma tissues and HBV-negative carcinoma tissues for the methylation of the remaining seven genes, including RUNX3, p14, WIF1, CDH1, PRDM2, SOCS1 and MGMT." (PMID 31772678, 2019). "The genes selected using this method included NCOA3, HOXA1, FOLR1, SOCS1, and PIK4CA, which showed similar expression patterns related to survival in patients with cancer." (PMID 29854877, 2018). "In particular, SOCS1 and SOCS3 are strong inhibitors of JAKs and can play pivotal roles in the development and progression of cancers." (PMID 28228755, 2017). "In order to determined role of some factors which are involved in cancer progression IDO, FASL, VEGF, SOCS1 and CCR7 were measured." (PMID 29299026, 2017). "Considering the potential effect of ROS generated during the therapy-induced response on cancer progression, we have investigated the anti-EMT function of SOCS1 through ROS regulation in colon cancer cells transduced with SOCS1 and shSOCS1." (PMID 27613835, 2016). "Aberrant methylation of tumor suppressor genes (TSG) such as SOCS-1, SOCS-3, SHP-1, and PRG2 has been documented in a variety of cancers including hematological malignancies, and is a plausible means by which cells can acquire therapy resistance." (PMID 26547689, 2015). "These novel insights will foster a paradigm shift in our understanding of SOCS1 regulated functions not only limited to CRC, but to other types of cancer as well." (PMID 26391193, 2015). "The KEGG pathway analysis results indicated that among 26 genes some of them were found to have roles in cancer related pathways like cell cycle (MCM2), Jak-STAT (SOCS1), MAPK (STMN1), PPAR signaling pathways (ME1)." (PMID 25978727, 2015). "Functional experiments have shown that inhibition of miR-155 induces elevated SOCS1 expression and the subsequent suppression of STAT3 in various cancers." (PMID 25823817, 2015). "For example, the sentence, S1, "[SOCS1]gene, [SOCS2] gene, [RASSF1a] gene, [CDKN2a]gene, and [MGMT]gene were [methylated]methylation in 75, 43, 64, 75, and 64% of [melanoma]cancer samples, respectively", contains 5 G-M pairs." (PMID 22168213, 2011). "SOCS1 and SOCS3 promoters are frequently methylated in primary tumors and cancer-derived cell lines, resulting in decreased expression of these negative regulators of Jaks and leading to sustained Jak activation." (PMID 17531096, 2007). "Given that SOCS1 is a non-redundant inhibitor of IFNγ signaling, SOCS1 expression in cancer cells would dampen PD-L1-mediated checkpoint inhibition." (PMID 38415248, 2024). "Stimulation of anti-miR155-transfected MDA-MB-231 cells with IFN-γ, significantly enhanced the SOCS1 mRNA expression compared to non-transfected cancer stimulated with IFN-γ (p<0.05)." (PMID 37720228, 2023). "In addition, Western blot analysis showed decreased SOCS1, but increased phosphorylated STAT1 (p-STAT1)/p-STAT3 ratios in miR-155–overexpressing primary cancer cells compared with controls." (PMID 35925680, 2022). "Increased expression of TLR4 is a distinctive characteristic of CAC that co-occurs with miR-155 upregulation alongside downregulation of suppressor of cytokine signaling 1 (SOCS1) and Src homology 2 domain-containing inositol-5′-phosphatase 1 in SW480 and HCT116 cancer cells." (PMID 35955886, 2022). "We did not identify significant differences in the expression of SOCS1 or SOCS7 between cancer and normal samples." (PMID 34120621, 2021). "Finally, the involvement of SOCS1, TAB2, and Foxp3 as direct targets for TNF-α gene in both cancer types was assessed." (PMID 34900737, 2021).
cancer (continued). "Moreover, a number of target genes of miR-155 affect other cancer-related processes, such as cell growth and survival (CCND1 and GAB3), cell adhesion junction (ANKRD6 and SMAD2), proliferation (SOCS1 and STAT3), and apoptosis (TP53BP1)." (PMID 31744065, 2019). "SOCS1 forms a negative feedback loop with miR-122a-5p and regulates cellular interactions involving cancer cells, mast cells and macrophages during PSA." (PMID 31597362, 2019). "SOCS-1 and SOCS-3 may promote cancer development through promoting the proliferation of cancer cell." (PMID 30788302, 2018). "JAK2 expression was downregulated in carcinoma tissue (FC 0.82) and SOCS1 expression was slightly upregulated in carcinoma tissue (FC 1.05), although this finding was not statistically significant." (PMID 30603058, 2018). "The frequency of SOCS-1 methylation in HCC cancer tissues is significantly higher than in adjacent non-tumorous tissues and benign liver tissues, but no prognostic effect of SOCS-1 methylation was observed in HCC patients." (PMID 28404963, 2017). "Among them, SOCS1 and SOCS3 are the critical molecules in the development of cancers." (PMID 28228755, 2017). "The roles of SOCS1 and SOCS3 in various types of cancer are still controversial." (PMID 28404963, 2017). "Hence, further investigation on the feasibility of SOCS1 and SOCS3 as potential cancer therapeutic targets has been conducted in many types of cancers." (PMID 28228755, 2017). "Based on such anti-oxidant effect of SOCS1 we have hypothesized that SOCS1 may prevent ROS-induced EMT and invasive property of cancer cells, and sought to investigate molecular mechanisms involved." (PMID 27613835, 2016). "In a general sense, it would suggest that SOCS, such as SOCS1, should be considered in circumstances where increased immune activity is desirable against infectious as well as non-infectious diseases such as cancer." (PMID 26617608, 2015). "SOCS1 was initially thought to be a potent inhibitor of the JAK-STAT pathway, which not only has a negative role in downregulating JAK signaling, but can also modulate other signaling pathways that can stimulate STAT activation, and is involved in the progression of various cancers." (PMID 37504269, 2023). "However, anticancer drugs activated by NRF2-induced enzymes such as NQO1 could be exploited in SOCS1-low/SOCS3-high HCC and other instances of NRF2-mediated cancer progression." (PMID 36765862, 2023). "Therefore, this study aims to further discuss the molecules and signal pathways regulating the expression and function of SOCS1 and SOCS3 in various types of cancers and elucidate the feasibility and efficiency of SOCS-based target therapeutic strategy in anticancer treatment." (PMID 28228755, 2017). "Results indicate a positive correlation between SOCS1 expression and TMB in cancers like COAD and BRCA, while a negative correlation was observed in LUAD and KIRP." (PMID 39654174, 2024). "Serum SOCS1, TAB2, and Foxp3 level in cachectic and non-cachectic pancreatic and NSCL cancer patients and cachexia severity." (PMID 34900737, 2021). "Expression level of miR-155, SOCS1, TAB2, and Foxp3 in cancer cachectic patients considering the cachexia severity, regardless of the cancer type." (PMID 34900737, 2021). "Nonetheless, interaction of SOCS1 with Elongins is dispensable for SOCS-dependent inhibition of JAK2 and overexpressed Elongins/SOCS1 do not destabilize wild-type JAK2 in cancer cells." (PMID 24833526, 2014).
cancer (continued). "In many cancer types, recent studies have demonstrated that the hypermethylation of SOCS-1 is not controlled by the JAK/STAT pathway, and IL-6 cannot perform a role in cancer defense; on the contrary, it is involved in cancer development." (PMID 19457231, 2009). "Negative modulation of SOCS1 and SOCS3 is a survival strategy in most cancer cells." (PMID 27190500, 2016).
infection (126 papers, 2005 to 2025). The state of being infected such as from the introduction of a foreign agent such as serum, vaccine, antigenic substance or organism. "Infection with HuCoV-OC43 caused an eight-fold induction of SOCS1 as well as SOCS3 (p < 0.01 for both), which was prevented in the presence of 30 μM pJAK2." (PMID 35799776, 2022). "Here, we advanced the field forward by demonstrating that myeloid-specific SOCS-1 inhibits phagocyte antimicrobial effector function, neutrophil migration to the site of the infection, and ultimately linked SOCS-1 actions to IFNα/β in vivo." (PMID 33690673, 2021). "Others have demonstrated that infection of bone marrow-derived macrophages with MCMV passaged through BALB/c-derived MEFs causes an increase in SOCS1 and SOCS3 mRNA expression levels from 2 to 24 hours after infection." (PMID 28182772, 2017). "Mice with a SOCS1 deficiency in their macrophages had a lower bacterial load in the lung a week after infection with Mycobacterium tuberculosis than did mice with normal SOCS1 expression." (PMID 26579124, 2015). "In contrast, albumin concentrations in SOCS1−/−IFN-γ−/− airways were significantly decreased at 11 dpi, indicating that SOCS1 deficiency is associated with attenuated lung vascular damage at the resolution phase of infection." (PMID 25500584, 2014). "SOCS1 was also associated with DENV-2 escape from IFN-λ response during infection." (PMID 32574254, 2020). "Although viral burdens at the early stage of infection (4 dpi) were comparable in WT and gene-deficient mice, SOCS1−/−IFN-γ−/− mice exhibited improved viral clearance at 7 dpi compared to both IFN-γ−/− and WT mice, as revealed by a10-fold decrease in viral burdens." (PMID 25500584, 2014). "Indeed, the computed top DEG, typifying each cluster on day 3 in the effector phase of infection, hosted several interferon-induced anti-viral genes (Irf1, Irf7, Ifrd1, Socs1, Socs3, Ifit1, Bst2, and Isg15) as well as genes associated with mature resident Trm cells (Cd69, Nfkbid, Brd2, FosB)." (PMID 35260804, 2022). "Among the transcripts involved in the subtle HIF-α program activated during infection with L. major were Socs1 and Mevf." (PMID 40191198, 2025). "Expression of the protein Suppressor of Cytokine Signalling-1 (SOCS-1) is also affected by infection." (PMID 40565065, 2025). "PBEC were able to be infected with IAV and infection caused an increase in expression of immune genes including CXCL10, IFNB1, ISG15 and SOCS1." (PMID 40496017, 2025). "S6, D to F), in contrast to other anti-inflammatory genes including Hmox1, Socs1, and Socs3, which were consistently increased in the expression near sites of infection." (PMID 39813329, 2025). "Infection of mice with B. malayi confirmed that expression of both GATA-3 and SOCS-1 is increased following infection in both macrophage-enriched adherent cells and lymphocyte enriched non-adherent cells." (PMID 40565065, 2025). "In the case of West Nile virus (WNV) and tick‐borne encephalitis virus, infection results in transcriptional upregulation of SOCS1 and SOCS3, which suppress antiviral cytokine responses." (PMID 40844207, 2025). "SOCS-1 is upregulated in macrophages 24 h after infection but expression remains elevated only in macrophages infected with transfected protozoa and not in macrophages infected with wild type protozoa." (PMID 40565065, 2025). "Further analysis of in vivo and in vitro infection with IAV revealed that overexpression of miR-19a/b impeded SOCS1, consequently suppressing the release of inflammatory mediators." (PMID 38435118, 2024). "The infection of BJ05/H1N1 in the expression of SOCS1 protein in a manner that was dependent on time." (PMID 38435118, 2024). "The increased SOCS1 response observed after infection of chicken organoids still confirms the relevance of the model." (PMID 37525204, 2023).
infection (continued). "Given the protective effect of pJAK2 peptide against HuCoV-OC43 infection, we tested if that effect was caused by blunting of the SOCS1 and/or SOCS3 response following the infection." (PMID 35799776, 2022). "We also show that infection of cells with this virus induces SOCS1 and SOCS3, and that pJAK2 eliminates this induction." (PMID 35799776, 2022). "During early infection, transcriptional factors associated with negative regulation of immune function, including IL1RN, SOCS1, and TRIM24 were downregulated." (PMID 33806942, 2021). "The autocrine nature of IFNβ signaling in macrophages would also explain why inhibition of SOCS-1 significantly improved infection outcomes at time points as early as 6 hours post-infection." (PMID 33690673, 2021). "During the process of model refinement in this paper, we have identified the ratio of SOCS1:SOCS3 as 3:2 for establishment of infection which is further exploited as a target for designing therapeutics." (PMID 35011356, 2021). "In our infection model, we detected increased expression of SOCS1, a target of miR-155, in lung macrophage of NK cell-depleted mice compared to control mice (data not shown)." (PMID 35059323, 2021). "We observed a gradual increase in skin Socs1 mRNA expression and protein levels at days 1 and 3 post-infection." (PMID 33690673, 2021). "The obtained data signify the anti-inflammatory role of IL6 in establishing SOCS1/SOCS3 immune axis during the early stage of infection." (PMID 35011356, 2021). "Our data show that Socs1 expression was significantly upregulated in the skin of hyperglycemic animals at both day 1 and day 3 post-infection when compared to euglycemic animals." (PMID 33690673, 2021). "Expression of SOCS-1 during infection correlates with reduced levels of the pro-inflammatory cytokines IL-1β, TNF-α, and IL-6 as well as antimicrobial NO and reactive oxygen species (ROS)." (PMID 33690673, 2021). "We have shown an increase in SOCS-1 expression in response to both IVA infection and IFN-λ1 stimulation of cells." (PMID 34452467, 2021). "Using synthetic biology approaches, peptide based immuno-regulatory circuits have been designed to target the activity of SOCS1 which can restore pro-inflammatory cytokine expression during infection." (PMID 35011356, 2021). "One of the possible inhibitors is the SOCS-1 protein, whose peak expression is observed approximately 10 h after infection." (PMID 33255985, 2020). "Collectively, PEDV infection upregulates SOCS1 expression by modulating host miR-30c-5p abundance at the late stage of infection." (PMID 32574254, 2020). "It has also been shown that infection of human tracheobronchial epithelial cells with IAV (subtypes H5N1 and H3N2) is associated with a significant increase in the expression of SOCS-1 and SOCS-3." (PMID 33255985, 2020). "Here, we show that human DCs rapidly upregulate SOCS3 expression after infection with wild-type H. pylori P12, whereas the induction of SOCS1 and SOCS2 expression is observed only at later time points." (PMID 33023610, 2020). "The antiviral gene Gig2-3 was especially highly expressed in the late phase, while suppressor of cytokine signaling 1 (SOCS-1) was down-regulated in the early phase of infection (E-III) followed by induction in the acute phase." (PMID 33013908, 2020). "Our data reveal that SOCS3 mRNA was already induced within 1 h of infection, whereas SOCS1 and SOCS2 expression was delayed and detectable only after 8 h." (PMID 33023610, 2020). "In summary, we determined that PEDV escaped IFN-λ response at the late stage of infection by downregulating miR-30c-5p, thus increasing SOCS1 expression." (PMID 32574254, 2020). "The expression of Socs1 and Socs3 were analyzed at 12 hours post infection and only the expression of Socs3 was reduced after ZY13 administration." (PMID 32849457, 2020). "Our data indicate a specific and strong upregulation of SOCS3 after 1 h of infection, while SOCS1 and SOCS2 displayed delayed kinetics." (PMID 33023610, 2020).